CD274 (CD274 molecule)
Diseases named in the same sentence as CD274 in open-access papers (continued):
Sharing a sentence is not in itself a finding about the gene and the disease.
tumor (continued). "CD274 (PD-L1), which is abundantly expressed in many tumours, induces apoptosis in CTL and helps tumour cells to evade immune surveillance by activating CD274 receptors on CTL (cytotoxic T lymphocytes), thereby increasing drug resistance in tumour cells and making them more difficult to treat." (PMID 38575994, 2024). "PD-L1/CD274, a protein on the surface of tumors that binds to PD-1 on the surface of T cells to weaken effector T cell responses, further induces immune suppression in tumor environments." (PMID 38622609, 2024). "In LAPTM4B-overexpressing patients, CD274 (PD-L1) overexpression on tumor surface suggests that treatment with PD-L1 antibodies may have therapeutic efficacy." (PMID 38388484, 2024). "Furthermore, checkpoint molecule PD-L1 (programmed death ligand 1; CD274) has been detected on the surface of plasma derived exosomes in HNSCC patients in correlation with the individual tumor- and lymph node status." (PMID 39304856, 2024). "Additionally, the response to tumor cells (GO:0002834) featured CD274 and AHR genes with a fold enrichment surpassing." (PMID 38658744, 2024). "We next evaluated the relationship between baseline CD8 infiltration (assessed by the mRNA expression level of CD8A), pretreatment tumor CD274 (PD-1 ligand 1) and KDR mRNA expression levels, and the T cell-inflamed gene expression profile of 15 biomarkers and the response to treatment." (PMID 38584166, 2024). "Indeed, myeloid cells associated with a favourable clinical response expressed transcripts associated with tumour-residing CCR7+ DCs, including CCR7, CD274, IL15, PVR and CD70." (PMID 38267413, 2024). "Firstly, we analyzed the expression of PD-L1 (CD274) in each tumor subpopulation." (PMID 38443340, 2024). "Consequently, in tumor cells after co-culture, we found that mRNA expression of CD274 was significantly downregulated in FTSJ1 KD cell lines and upregulated in FTSJ1 OE cell lines compared to the control cell line." (PMID 38339348, 2024). "Furthermore, CXCL11 is involved in tumor lymphatic cross talk and the regualtion of checkpoint molecule PD-L1 (CD274) in cancer tissues." (PMID 38609887, 2024). "PD-L1 (also known as CD274 or B7-H1), the dominant ligand of PD-1, belongs to the B7 family and can be expressed not only by immune cells, such as T cells, B cells, macrophages, DCs, and mast cells, but also by normal tissue cells and aberrant tumor cells." (PMID 38177102, 2024). "Programmed death ligand 1 (PD-L1; also known as CD274 or B7-H1) is an immunosuppressive molecule expressed on the surface of tumor cells and immune cell membranes that interacts with programmed death 1 (PD-1) receptors on the surface of T lymphocytes to negatively regulate T cell functions." (PMID 39090096, 2024). "An example is a case report on a patient resistant to multiple therapies, including R-CHOP plus enzastaurin and gentamicin + oxaliplatin (GemOx) with lenalidomide and selinexor, who harbored a CD274 amplification and exhibited a high PD-L1 tumor proportion score." (PMID 39518937, 2024). "Thus, the general patterns of regulation: pTERTmut repression of CD8+ and NK cytotoxic cells with or dendritic cells; and relatively high levels of CD276/B7-H3 and CD274/PD-L1 were exhibited by both tumor sample cohorts." (PMID 39717106, 2024). "Subsequently, we found that patients with structural variants in CD274 UTR region who responded to immune checkpoint inhibitors were all positive for PD-L1 expression validated by mIF method, which confirmed the immune escape behavior of tumor cells." (PMID 36717553, 2023). "A study showed that nearly two-thirds of ovarian tumors had a modest expression of CD274 mainly on immune cells rather than tumor cells, which was associated with the worst prognosis." (PMID 36979400, 2023).
tumor (continued). "Thus, we examined the relationship between PD-L1 tumor proportion score (TPS) as measured by the 22C3 IHC assay and CD274 gene expression from whole-transcriptome RNA-seq of bulk tumor tissue." (PMID 35881197, 2023). "Of note, these tumor-specific neutrophils might act as tumor promoters by overexpressing Vegfa, Cd274, Pdcd1lg2, and Lgals3, leading to these cells being further defined as tumor-promoting neutrophils." (PMID 36650153, 2023). "Furthermore, tumor samples with a desmoplastic growth pattern exhibited a significantly decreased percentage of CD274- and CD206-positive cells in all monocyte populations compared to non-desmoplastic samples." (PMID 37370832, 2023). "PD‐1 (CD279) and PD‐L1 (CD274 and B7‐H1) were immune response suppressors that, when combined, could suppress tumor immunity and induce T‐cell apoptosis via a variety of mechanisms." (PMID 36880420, 2023). "The CD274 ferroptosis-driver score was confirmed as an independent parameter for the overall survival of the patients according to the inclusion of age at diagnosis and Tumor, Nodes and Metastasis stage classification in the multivariate model." (PMID 38201582, 2023). "Programmed death ligand-1 (PD-L1), encoded by the CD274 gene, is an immune checkpoint inhibitor that, when expressed on the surface of tumor or on antigen presenting cells (APC), binds to programmed death-1 (PD-1) on T lymphocytes, inhibiting their immune function." (PMID 37603071, 2023). "In recent years, numerous studies have shown that cancer cells expressing CD274 may have an impact on regulatory T cells in the tumor microenvironment." (PMID 37178414, 2023). "This ligand known as PD-L1 or CD274 is expressed on the surface of a tumor and various other cells." (PMID 38201509, 2023). "With the biomarker assessment module of the TIDE website, we evaluated the accuracy of PES1 in five ICB HNSCC cohorts and compared it with other published biomarkers associated with tumor immune evasion, including CD274 (PD‐L1), MSI Score, CD8, Merck18, and IFNG." (PMID 37076985, 2023). "CD274 expression was down-regulated in LUAD tumor tissues in the GEPIA database." (PMID 36959799, 2023). "In addition, silencing RAP2C-AS1 down-regulates the expression of immune checkpoint genes such as CD274, reflecting its role in the tumor immune microenvironment." (PMID 38071230, 2023). "PDCD1 regulates T-cell activity by binding to CD274 or PD-L2 on the surface of tumor cells." (PMID 36979400, 2023). "Interestingly, ZNF714 expression showed a positive association with the expression of CD274, which is a gene coding for PD-L1, a checkpoint protein that blocks T cell activation, allowing the tumor to evade the immune system." (PMID 37958512, 2023). "The enhanced repression of tumor growth was accompanied by increased tumor STAT-1 signaling, as reflected by the increased expression of STAT-1 target genes, including Cd274 (encodes PD-L1)." (PMID 37500611, 2023). "As a ligand for the inhibitory receptor PDCD1, CD274 could mediate anti-tumor immune escape by regulating the activation threshold of T cells and limiting T-cell effector responses." (PMID 37663248, 2023). "CD274, also known as PD-L1, is expressed by tumor cells in the tumor microenvironment." (PMID 37197424, 2023). "Therefore, the immunosuppressive role of tumor CD274 overexpression is likely more prominent in non‐MSI‐high tumors, whereas that of F. nucleatum is more prominent in MSI‐high tumors." (PMID 37538192, 2023). "Immune checkpoints such as programmed death ligand 1 (PD-L1; encoded by the CD274 gene) and PD-1 are elevated in cancers and their activated interaction results in the evasion of immune surveillance and the facilitation of tumor malignant transformation." (PMID 37686533, 2023). "Furthermore, our analysis revealed that the expression level of ZNRF2 is positively correlated with the immunosuppressive molecule CD274 in various tumours, and in THCA, it is positively correlated with Tregs." (PMID 37551845, 2023).
tumor (continued). "Notably, CD274 (PD-1) exhibits a significant positive correlation with GARS1 expression in 15 cancer types, emphasizing the strong association between GARS1 and tumor immunotherapy." (PMID 37404826, 2023). "Furthermore, differential analysis showed vascular-related genes FLT1, TMB, neoantigen, PD-L1 protein (CD274), Tumor Immune Dysfunction and Exclusion (TIDE), and T cell exclusion score were significantly different between the high- and low-risk groups." (PMID 37189138, 2023). "Moreover, risk scores were negatively related to the expression of CD274, CTLA4, ICOS, LAG3, PDCD1, and PDCD1LG2 and negatively correlated with CD8+, CD4+, and Treg tumor-infiltrating immune cells." (PMID 37674251, 2023). "Today, the two most successfully exploited immune checkpoints are CD279, called programmed cell death protein 1 (PD-1), expressed on tumour infiltrating lymphocytes, B cells, NK cells, and myeloid cells; and its ligand, CD274, called programmed death-ligand 1 (PD-L1), expressed on tumour cells." (PMID 37345033, 2023). "Interestingly, we examined PD-L1 (CD274) expression in our ex vivo sorted tumor cells and found that PD-L1 (CD274) is upregulated by 2.56-fold (padj = 1.46E-10) in sh-B7-H3 tumor cells compared to sh-NC." (PMID 36869048, 2023). "Previous data have indicated that cytokines, such as IL2, IL6, TGF-β, and CXCL5, in an immune-reactive TME, may stimulate CD274 expression on tumor cells through distinct signaling, potentially representing one of the causes of immune tolerance." (PMID 37898619, 2023). "The product of the CD274 PD-L1 gene was highly expressed on CD71+TER119+ tumor-infiltrating cells." (PMID 37894821, 2023). "PD-L1, also known as CD274 or B7-H1, is important for tumor progression and immune escape." (PMID 36977072, 2023). "At the same time, it was found that low CD274 had high tumor initiation potential." (PMID 37592311, 2023). "Furthermore, TSPO expression positively correlated with PD-L1 (CD274), which is induced in response to the activity of tumor-infiltrating T cells in various tumors." (PMID 37158962, 2023). "CD274 messenger RNA expression was correlated with pathological tumor regression." (PMID 37488287, 2023). "Notably, CD274 (PD-L1) exhibited the most significantly higher expression in B4GALT1-high tumours than in B4GALT1-low tumours." (PMID 37303063, 2023). "Our analysis suggests that, of the three immune checkpoints considered, PDCD1/CD274 is the least important determinant of the exhausted CTL state; however, our model remains compatible with PDCD1/CD274 playing a role in CTL exhaustion at early time points after CTL infiltration of the tumor." (PMID 37182110, 2023). "Taken together, our results suggested that upregulation of CD40, CTLA4, ARG1, STAT3, IDO, and CD274, which were included in tumor inflammation signature, in the TME of KRASmut, could be characteristic of immune suppression." (PMID 36831441, 2023). "We found that pre-treatment gene expression levels of PDCD-1, but not CD274 (gene that encodes PD-L1), was statistically significantly associated with reduction in tumor size." (PMID 37188783, 2023). "With our model we were able to obtain good fits if the exhausted state was correlated with HAVCR2 or LAG3 but not with PDCD1/CD274, which was due to the early peak of Pdcd1 and Cd274 transcription that was already well in decline on day 5 while CTL numbers in the tumor remained high." (PMID 37182110, 2023). "Furthermore, overactivation of STAT3 can promote tumor progression by inducing the polarization of type M2 macrophages and the expression of CD274." (PMID 37724127, 2023). "The upregulation of Ctla4 and Lag3 was rather specific as no significant changes were observed in mRNA levels of Cd80 and Cd86 (two CTLA4 ligands present in the antigen-presenting (tumour) cells), Tim-3/Galectin-9 (Havcr2/Lgals9), and Pd-l1 (Cd274) immune checkpoints." (PMID 36433941, 2022).
tumor (continued). "The immune checkpoint genes evaluated included CD274, also known as PD-L1, that encodes an immune inhibitory ligand expressed by hematopoietic and nonhematopoietic cells such as T cells and various tumor cells." (PMID 35198632, 2022). "The tumor nodal stage is suggestively correlated with CD274 expression." (PMID 35204406, 2022). "Several mechanisms are involved in CD274 expression improvement on tumor cells, such as the activation of intracellular signaling pathways (MAPK and PI3K-Akt), the enhanced activity of transcription factors (STAT3), and a rising occurrence of inflammatory mediators (interferon-γ and interleukin-6)." (PMID 36013315, 2022). "Therefore, overexpression of the CD274 molecule in the tumor microenvironment compromises immune response." (PMID 36013315, 2022). "Recently, a scRNA-seq study of six metastatic omental tumors that derived from primary HGSOCs unraveled the genetic signatures of immune cell subsets within the tumor microenvironment and identified NR1H2+ IRF8+ and CD274+ macrophage clusters, which were suggested with an anti-tumor response." (PMID 35935940, 2022). "Programmed death-1 (PD-1, also known as CD279) is an immune checkpoint protein expressed on the surface of T cells and is responsible for the suppression of the antitumor immune response by binding to the programmed death ligand-1 (PD-L1, also known as CD274 or B7 homolog 1) on tumor cells." (PMID 36358638, 2022). "Some studies reported a low rate of CD274 expression in this tumor, ranging from 9% to 12%." (PMID 36013315, 2022). "The integrated area under the curve (AUC) of the CAF signature, tumor mutation burden (TMB) and combined expression of CD8, CD274, and Merck18 was 0.776, which was higher than the AUC of TMB (AUC = 0.571) as well as the AUC of the expression of immune checkpoints (AUC = 0.760)." (PMID 36568368, 2022). "Thus, there is an urgent need to understand how CD274 levels on intra‐tumoural compartments influence tumour growth and predict treatment response." (PMID 35802807, 2022). "Moreover, these WT HRD-high tumors also appeared to have significantly higher tumor mutational burden (TMB), and higher CD274 (PD-L1) expression than WT HRD-low tumors." (PMID 36401316, 2022). "Cd274 (PD-L1) was poorly expressed in the cancer cells and immune populations of both tumor types." (PMID 36311166, 2022). "In addition, in this study the expression of HLA family members and several immunotherapy-related target genes, such as CD274 (PD-L1), CTLA-4, and LAG-3, was elevated in the tumor environment of the high-risk group compared with the low-risk group." (PMID 36081499, 2022). "Additional correlation analyses showed that IL7R expression was significantly associated with markers of cells involved in immunosuppression such as CD68, CD163, MRC1, and IL10 (tumor‐associated macrophages), CD4, FOXP3 (regulator T lymphocytes) and CD274 (PD‐L1)." (PMID 36054746, 2022). "Besides these scores, the XP genes, immune-specific single genes (CD8A, CXCL9, CD274, and CXCL13) and tumor mutational burden (TMB) were cross-correlated." (PMID 35174087, 2022). "To comprehensively inspect the immune microenvironment of HCC TME, we firstly compared gene expression of immune inhibitory checkpoint molecules between tumor tissues and normal (peri-tumor) tissues, including CD274, CTLA4, HAVCR2, LAG3, PDCD1, PDCD1LG2, TIGIT, and SIGLEC15." (PMID 35444645, 2022). "Notably, serum miR-155 abundance also mirrored the expression levels of the immunosuppressive molecule CD274 (PD-L1) in tumor tissues." (PMID 35925680, 2022). "To understand how cefepime regulates tumor PDL1 protein content, we first assessed Cd274 mRNA-encoding PDL1 in ID8agg and B16 cells; however, it was not reduced in either cell line." (PMID 35563520, 2022).
tumor (continued). "In addition, since FREM2 mutation was associated with immune infiltration, we analyzed its association with the expression levels of PDCD1, CD274, CTLA4, LAG3, TIGIT, and HAVCR2, which are important immune checkpoints responsible for tumor immune escape." (PMID 35252356, 2022). "SOCS1, CD274, and SOX11 associated with miR-155 and miR-215 in the regulation hub suggested exerting vital functions in tumor immunology, whether through the miR-155, miR-215 pathway or not." (PMID 35433461, 2022). "These hub genes showed remarkably associated with immune checkpoints (CD274, PDCD1 and CTLA4), which suggested that these hub genes may play an important role in tumor immune escape in HCC patients." (PMID 35637248, 2022). "In this context, evaluating CD274 in neoplastic cells and tumor-infiltrating immune cells could be helpful." (PMID 36013315, 2022). "Among ICIs, the representative (PDCD1,PD-1) inhibitor, its (CD274,PD-L1) inhibitor, and cytotoxic T-lymphocyte associated protein 4 (CTLA4) restore the ability of immune cells to fight tumors by counteracting the inhibition of the immune system by tumor cells." (PMID 35600371, 2022). "HCP5 was certified to promote tumor growth and upregulate PD-L1/CD274 expression." (PMID 35601830, 2022). "Notably, tumor-infiltrating macrophages in tumor-bearing Ern1 (-/-) mice had a marked reduction in spliced Xbp1, Il-23p19, Arg1 and Cd274 gene expression compared to their Ern1 fl/fl counterpart." (PMID 35237269, 2022). "PANX1 may promote tumor progression and immune suppression by co-expression of immunoinhibitors, such as CD274, PDCD1LG2, and TGFBR." (PMID 34796785, 2021). "The immune checkpoint molecule PD-L1 (CD274) is a crucial regulator of the tumor immune response." (PMID 33951601, 2021). "CD274 upregulation also suppresses anti-tumor immunity in various human cancer types." (PMID 35008821, 2021). "Therefore, we evaluated the relationship between the expression of immune inhibitory molecules (TIGIT, PDCD1LG2, PDCD1, LAG3, HAVCR2, CTLA4, and CD274) in the immune ignorant, immune inactive, and hot tumor subtypes." (PMID 33777927, 2021). "Immune cells may recognize and kill tumor cells faster, but there is also immunosuppression (increased expression of CD274)." (PMID 34635662, 2021). "This study took LUAD as the research disease, focusing on the analysis of immunotherapy-related programmed death-ligand 1 (PD-L1, also called CD274) expression, tumor-infiltrating lymphocytes (TILs), and tumor microenvironment (TME) characteristics between Asians and Caucasians." (PMID 34933667, 2021). "Furthermore, the expression of CD274 and PDCD1LG2 was correlated with tumor mutation burden (TMB), microsatellite instability (MSI), mismatch repair (MMR), and DNA methyltransferase (DNMT) of different types of cancers." (PMID 33833994, 2021). "The CD274 gene, encoding for PD-L1, is located on chromosome 9p24.1: genomic rearrangements may upregulate CD274 expression, leading to enhanced immune escape of tumor cells." (PMID 34830209, 2021). "Additionally, PD-1 (PDCD1) and PD-L1 (CD274) expression play an important role in tumor immune escape." (PMID 34168239, 2021). "Interestingly, both CD274 mRNA and PD-L1 protein expression increased in tumor tissue from the GSK591-treated group." (PMID 35111150, 2021). "While, CMS1 tumors exhibit potent anti-tumor activity, transcription of genes encoding ICs such as PDCD1, CD274, CTLA4, and LAG3 may aid tumor immune escape in these tumors." (PMID 33477864, 2021). "In addition, the association between CD274/PDCD1LG2 and the tumor infiltration level, tumor mutation burden (TMB), microsatellite instability (MSI), mismatch repair (MMR), and DNA methyltransferase (DNMT) were analyzed in the different tumor types." (PMID 33833994, 2021).